SMAD3 (SMAD family member 3)
Diseases named in the same sentence as SMAD3 in open-access papers (continued):
Sharing a sentence is not in itself a finding about the gene and the disease.
pulmonary fibrosis (continued). "TAGLN2 was identified as a biomarker in the development of pulmonary fibrosis since it triggered the activation of the TGF-beta/Smad3-pathway." (PMID 38322285, 2023). "We found that the expression of Smad3 in the lung tissue of mice with BLM-induced pulmonary fibrosis was higher than that in the saline group, and the expression of Smad3 in the BLM + HYAP group was lower than that in the BLM group." (PMID 36422524, 2022). "miR-489 inhibited total SMAD3 and phosphorylated SMAD3 (p-SMAD3) levels and alleviated pulmonary fibrosis in mice and fibroblasts." (PMID 35096264, 2022). "Smad3 is a potent transcriptional factor for FMT marker gene expression in pulmonary fibrosis and subepithelial fibrosis in asthma." (PMID 35197539, 2022). "LOXL2 lies upstream of Smad3 in that silencing LOXL2 inhibited the expression of pSmad3 in lung fibroblasts of bleomycin-induced pulmonary fibrosis mice." (PMID 36159334, 2022). "Smad3 is one of the signaling proteins in the TGF-β pathway involved in the development of pulmonary fibrosis." (PMID 36499287, 2022). "JAK2 also promotes pulmonary vascular remodeling through Smad3 sensitization in idiopathic pulmonary fibrosis models." (PMID 35432718, 2022). "Firstly, epithelium-specific disruption of TGF-β RII receptor increases Smad2 phosphorylation and decreases Smad3 phosphorylation, and protects mice from bleomycin-induced pulmonary fibrosis with increased survival." (PMID 35269498, 2022). "Recently, TanIIA was found to ameliorate silica-induced pulmonary fibrosis through the removal of triggering of the Nrf2 pathway, dephosphorylation of Smad3, and elevation of Smad7." (PMID 35432718, 2022). "The mechanism of intracellular transduction initiated by TGF-β in the induction of pulmonary fibrosis entails receptor-mediated Smad3 signaling." (PMID 35269498, 2022). "In the IPF model, fibroblast-intrinsic CD274 is required for the development of pulmonary fibrosis through interaction with SMAD3, resulting in further activation of the Wnt-/βCathenin pathway." (PMID 36009475, 2022). "The administration of short hairpin RNA (shRNA) expressed in adenoviral vectors suppressed the expression of Smad3 in the L929 cell line, while in the paraquat-induced pulmonary fibrosis, it led to slower collagen deposition and pulmonary fibrosis development." (PMID 36499287, 2022). "For instance, Sirt1 activation or overexpression can inhibit pulmonary fibrosis in vitro via inactivation of TGF-β1/Smad3 and mTOR signaling." (PMID 34925016, 2021). "Astragaloside IV combined with ferulic acid regulated the oxidative stress of lung tissues and TGF-β1/Smad3 signaling through miR-29b, thereby reducing the degree of pulmonary fibrosis." (PMID 33763150, 2021). "Upregulated lncRNA H19 in tissues from IPF patients downregulates miR-140 and modulates TGF-β/Smad3 signaling, and further in vivo and in vitro experiments show that the knockdown of H19 diminishes pulmonary fibrosis." (PMID 34819948, 2021). "The combination of astragaloside IV and ferulic acid reduced oxidative stress, collagen synthesis, and inhibited the TGF-β1/Smad3 signaling pathway through miR-29b regulation, thereby reducing the damage from pulmonary fibrosis." (PMID 33763150, 2021). "The critical role of TGF-β in high-fat diet associated lung fibrosis has been assessed with the use of genetic modified animal models and pharmaceutical approaches targeting TGF-β/Smad3 signaling." (PMID 35082682, 2021). "The same mechanisms involving TGF-β/Smad3 signaling were described for miR-29b inhibition in bleomycin-induced pulmonary fibrosis and the development of progressive renal fibrosis in obstructive nephropathy." (PMID 35118144, 2021). "The mechanism is attributed to the ability of ginsenoside Rg3 to reduce the nuclear localisation of HIF-1α and inhibit the evolution of EMT-related pulmonary fibrosis mediated by the TGF-β1/Smad3 signalling pathway." (PMID 33639908, 2021).
pulmonary fibrosis (continued). "MiR-29 can also directly act on the 3′-UTR of the target gene TGF-β1, inhibit the transcription of TGF-β1 mRNA, and reduce pulmonary fibrosis through the inhibitory effect of the TGF-β1/Smad3 signaling pathway." (PMID 33763150, 2021). "Smad proteins were the main signal transducers of the TGF-β signaling pathway, in which Smad3 binds to Smad4, forms a complex and enters the nucleus to regulate the targeted gene transcription, which thereby interferes with the formation of lung fibrosis." (PMID 33953686, 2021). "In conclusion, we demonstrated that disruption of the CRBN gene prevented the development of BLM-induced lung fibrosis by suppressing SMAD3 phosphorylation in lung fibroblasts." (PMID 34002012, 2021). "Elevated CCN1 in response to lung injury induced profibrotic gene expression via the TGF-β1/SMAD3 pathway leading to lung fibrosis." (PMID 33105556, 2020). "TGF-β/Smads signaling appears to be critical in pulmonary fibrosis, and Smad3’s key role in TGF-β-induced deposition of ECM has been widely recognized." (PMID 33381023, 2020). "Our experiment demonstrated that Schisandra inhibited pulmonary fibrosis as mediated by TGF-β1/Smad3/4 signaling pathways." (PMID 32884941, 2020). "Transgelin has been identified as a direct target of TGF‐β/Smad3 signaling in alveolar epithelial type II cells in lung fibrosis." (PMID 32583562, 2020). "To further study the effect of cinobufagin on TGF-β1/Smad3 signaling and pulmonary fibrosis, we performed follow-up in vitro and in vivo experiments." (PMID 31572194, 2019). "Inhibition of TGF-β1 signaling by Smad3 inactivation was partially resistance to pulmonary fibrosis." (PMID 30922349, 2019). "During the development of pulmonary fibrosis, phosphoinositide-3-kinase-protein kinase B (PI3K-Akt) signaling pathway caused activation of phosphorylation of Smad2 and deactivation of Smad3 (Zhao and Geverd, 2002)." (PMID 31611754, 2019). "In the present report, it was shown that there was more severe pulmonary fibrosis and activation of Smad3 in the lung tissues of Sdc4KO mice when compared to WT mice." (PMID 31600983, 2019). "Another protein, TAGLN (transgelin), is a direct target of TGFβ-/Smad3-dependent epithelial cell migration in lung fibrosis." (PMID 30774578, 2019). "A major process involved in pulmonary fibrosis development is the differentiation of fibroblasts into myofibroblasts, which requires Smad2/Smad3/α-SMA activation." (PMID 31905700, 2019). "Our results showed that vitamin D deficiency aggravated pulmonary TGF-β1 upregulation and subsequent Smad3 phosphorylation in BLM-induced lung fibrosis." (PMID 31775746, 2019). "Neutrophil elastase activated the Smad2/Smad3/α-SMA pathway to induce collagen deposition, while sivelestat abrogated the increased severity of pulmonary fibrosis caused by PM." (PMID 31905700, 2019). "A recent study shows that kidney-enriched lnc-TSI inhibits renal fibrogenesis by negatively regulating the TGF-β/Smad3 pathway, a classic pathway involved in the development of pulmonary fibrosis, indicating the important role of lncRNA in fibrotic lesions." (PMID 31273058, 2019). "SMAD3 was reported to play a critical role in pulmonary fibrosis through inducing expressions of several profibrotic mediators including CTGF." (PMID 29499695, 2018). "In lung epithelial cells that are implicated in pulmonary fibrosis, TGF-β activates Smad3 and the focal adhesion kinase (FAK) to mediate EMT and fibrotic marker expression such as α-SMA." (PMID 29701666, 2018). "One of the key processes in pulmonary fibrosis is the activation of fibroblasts into myofibroblasts, a process that seems to be dependent on activation of the activator protein (AP)-1 and SMAD3 pathway." (PMID 29499695, 2018). "Additional ECM components, including connective tissue growth (CTGF) and MMP2 are regulated by Smad2 or Smad3 in lung fibrosis." (PMID 29701666, 2018).
pulmonary fibrosis (continued). "In fact, RA exhibits anti-proliferative, anti-inflammatory, anti-migratory and anti-fibrogenic activities and ameliorates bleomycin-induced lung fibrosis by downregulating the TGF-β1/Smad3 signalling pathway in rats." (PMID 30134568, 2018). "Smad3 expression was shown to be downregulated in a model of bleomycin (BLM)-induced pulmonary fibrosis and in ureteral obstruction-induced kidney fibrosis, resulting in increased expression of a-SMA." (PMID 29039786, 2017). "Proinflammatory cytokines TGF-β1 after lung injury contributes in the formation of pulmonary fibrosis through receptor mediated phosphorylation of Smad2 and Smad3." (PMID 28496412, 2017). "HYDAMTIQ, a selective PARP-1 inhibitor, down-regulated the expression of TGF-β and p-Smad3, and thus exhibited an anti-fibrotic effect in bleomycin-induced lung fibrosis." (PMID 28423499, 2017). "PD also suppressed upregulation of TGFβ‐Smad3 signalling pathway and epithelial–mesenchymal transition, which was reported playing critical roles in lung fibrosis." (PMID 28609013, 2017). "The level of Smad3 gene methylation, mRNA expression, and the extent of pulmonary fibrosis in patients with PBL were analyzed based on Pearson correlation coefficients." (PMID 28562330, 2017). "We investigated the relationship between Smad3 gene methylation and pulmonary fibrosis in pigeon breeder's lung (PBL)." (PMID 28562330, 2017). "Our study found that Smad3 was involved in the development of pulmonary fibrosis in patients with PBL and that Smad3 gene methylation was the cause of abnormal Smad3 mRNA expression." (PMID 28562330, 2017). "Administration of UCHL5 inhibitor, b-AP15, reduced the expression of FN, type I collagen, Smad2/Smad3, and the deposition of collagen in lung tissues in a bleomycin-induced model of pulmonary fibrosis." (PMID 27604640, 2016). "Here, we demonstrate that UCHL5 de-ubiquitinates and stabilizes Smad2 and Smad3, thereby promoting TGFβ-1 signaling and contributes to the pathogenesis of pulmonary fibrosis." (PMID 27604640, 2016). "Smad3 induces fibroblast-to-myofibroblast transdifferentiation and Smad3-/- mice are protected from bleomycin-induced lung fibrosis." (PMID 27494713, 2016). "This study is the first to report that miR-489 attenuates silica-induced pulmonary fibrosis by directly repressing MyD88 and Smad3, and that it is regulated by CHRF." (PMID 27506999, 2016). "But the role of UCHL5 in regulation of Smad2/Smad3 and pathogenesis of pulmonary fibrosis is still unclear." (PMID 27604640, 2016). "Disruption of TGF-β1 signaling by Smad3 inactivation has also been shown to promote emphysema and resistance to pulmonary fibrosis." (PMID 26753996, 2016). "In conclusion, we demonstrate that UCHL5 de-ubiquitinates and stabilizes Smad2 and Smad3, promotes TGFβ signaling, and contributes to the pathogenesis of pulmonary fibrosis." (PMID 27604640, 2016). "Next, we examined levels of UCHL5, Smad2 and Smad3 in murine lungs from a bleomycin-induced pulmonary fibrosis model." (PMID 27604640, 2016). "The overexpression of miR-489 blocked pulmonary fibrosis both in vivo and in vitro by regulating its target genes MyD88 and Smad3, which are critical mediators in the inflammation and fibrotic signaling pathways, respectively." (PMID 27506999, 2016). "In summary, these studies identify an important role for Smad3 in regulating αvβ6 integrins and the potential for dysregulation of this pathway to impact on pulmonary fibrosis." (PMID 27494713, 2016). "This is the first study to identify that UCHL5 plays a pro-fibrotic role in the pathogenesis of pulmonary fibrosis through stabilization of Smad2/Smad3 and enhance in TGFβ-1 signaling in HLF and a murine model of pulmonary fibrosis." (PMID 27604640, 2016). "Previous studies demonstrated that the inhibition of pulmonary fibrosis exerts antifibrotic effects via the modulation of the TGF-β1/Smad-3 signaling pathway in repetitive OVA-challenged mice." (PMID 27741312, 2016).
pulmonary fibrosis (continued). "Most notably, these results strongly suggest that lncRNA CHRF, by targeting miR-489, regulates its targets MyD88 and Smad3 and participates in activating inflammation and pulmonary fibrosis." (PMID 27506999, 2016). "Transforming growth factor β-1 (TGFβ-1)-induced phosphorylation of transcription factors Smad2 and Smad3 plays a crucial role in the pathogenesis of idiopathic pulmonary fibrosis (IPF)." (PMID 27604640, 2016). "Our molecular study further demonstrated that miR-489 inhibited silica-induced pulmonary fibrosis primarily by repressing its target genes MyD88 and Smad3." (PMID 27506999, 2016). "Recently, besides TGF-β/Smad3 signaling, the signaling loop of IL-6/gp130/Stat3 has been shown to play a crucial role in the pathogenesis of lung fibrosis." (PMID 26289430, 2015). "Cav1 modulates SMAD2 and SMAD3 nuclear accumulation in fibroblasts in an experimental model of idiopathic pulmonary fibrosis." (PMID 25550395, 2015). "In pulmonary fibrosis Erk5 also appears to be necessary for the production of ECM by fibroblasts and epithelial cells, however, in this case it is associated with Smad3 acetylation; acetylation of Lys19 on Smad3 enhances the binding of Smad3 to DNA." (PMID 24795631, 2014). "The lung phenotype in pulmonary fibrosis is regulated by aberrant recapitulation of the TGF-β1/Smad3 pathway." (PMID 23967091, 2013). "These various experimental approaches demonstrate the direct implication of Smad3 activation on downstream TGF-β in the pathogenesis of pulmonary fibrosis." (PMID 23418473, 2013). "In summary, our results demonstrate that low-dose PTX prevents EMT transition and ameliorates pulmonary fibrosis by upregulating miR-140 expression to further suppress the TGF-β1/Smad3 pathway, which highlighted a new way for pulmonary fibrosis therapy." (PMID 23967091, 2013). "This study provides the evidence of an important role of low-dose PTX in ameliorating EMT and pulmonary fibrosis by upregulating miR-140 to suppress the activities of TGF-β1/Smad3 pathway." (PMID 23967091, 2013). "Collectively, our results demonstrate that low-dose PTX prevents pulmonary fibrosis by suppressing the TGF-β1/Smad3 pathway via upregulating miR-140." (PMID 23967091, 2013). "Then, we treated TGF-β1-stimulated AECs and bleomycin (BLM)-induced pulmonary fibreosis rats with PTX to verify the antifibrotic effect of PTX on pulmonary fibrosis and to clarify the underlying mechanisms involved in the TGF-β1/Smad3 pathway." (PMID 23967091, 2013). "Our results demonstrated that low-dose PTX reversed the TGF-β1-induced EMT in A549 cells as well as RLE-6TN cells, and improved the BLM-instilled pulmonary fibrosis in rat lungs with miR-140 upregulation and Smad3/p-Smad3 diminishment." (PMID 23967091, 2013). "Our results showed that PTX treatment not only suppressed TGF-β1-activated Smad3/p-Smad3 at mRNA or protein levels to further reverse subsequent EMT in A549 cells, but also downregulated p-Smad3 levels to improve subsequent pulmonary fibrosis in rat lungs." (PMID 23967091, 2013). "Abnormal TGF-β1/Smad3 activation plays an important role in the pathogenesis of pulmonary fibrosis, which can be prevented by paclitaxel (PTX)." (PMID 23967091, 2013). "Increasing evidence shows that down-regulation of miR-29 is associated with fibrosis in a number of disease models including ischemic cardiac remodeling, while overexpression of miR-29b is capable of inhibiting Smad3-mediated kidney and lung fibrosis." (PMID 23894614, 2013). "After exposure to BLM for 28 days, notable pulmonary fibrosis was observed, and strong staining of Smad3, p-Smad3 and α-SMA in AECs was also revealed as a prominent feature of BLM-induced rat lung tissues compared to BLM-untreated or sham control tissues." (PMID 23967091, 2013). "This concept is supported by the observation that two distinct Smad3 null mutations protect mice from bleomycin-induced lung fibrosis as well as TGF-β-induced lung fibrosis." (PMID 22684844, 2012).
pulmonary fibrosis (continued). "Considering its importance in the development of lung fibrosis, research directed at investigating the factors that control TGFβ1/Smad3 signaling has intensified." (PMID 22997505, 2012). "TGFβ1/Smad3 signaling stimulates connective tissue expression and epithelial-mesenchymal transition, events considered key to the development of lung fibrosis." (PMID 22997505, 2012). "AG administration dose-dependently reduced the phosphorylation of Smad2 and Smad3 protein in the bleomycin-induced pulmonary fibrosis (p < 0.05, p < 0.01)." (PMID 19552800, 2009). "TGF-β1 plays a key role in the pathogenesis of pulmonary fibrosis, and the Smad3 pathway is involved in fibrogenesis." (PMID 16438734, 2006). "The results obtained were consistent with the reported data, that is, the expression of Smad3 mRNA was down-regulated at an early stage of inflammatory injury during bleomycin-induced pulmonary fibrosis (Lane 2)." (PMID 16438734, 2006). "It has been reported that the expression of Smad3 mRNA was down-regulated at an early stage of inflammatory injury during bleomycin-induced pulmonary fibrosis, and the expression of Smad2 mRNA remained unchanged after bleomycin administration." (PMID 16438734, 2006). "Moreover, through its modulation of Nrf2/Nox4 redox equilibrium and TGF-β1/Smad3 signaling pathways, vitamin C exerts a protective effect against PQ-induced pulmonary fibrosis." (PMID 40290659, 2025). "Additionally, Wang and colleagues reported that, aside from downregulating TGF-β1/Smad3, resveratrol alleviated pulmonary fibrosis by downregulating lipopolysaccharide (LPS)/toll-Like Receptor 4 (TLR4)/Nuclear factor kappa B (NF-κB) signaling pathways in rats." (PMID 38474385, 2024). "These may suggest that DsbA-L affects pulmonary fibrosis by regulating the positive feedback loop of the TGF-β1/SMAD3 pathway." (PMID 39580448, 2024). "TGF-β could induce PD-L1 to interact with Smad3, suggesting that PD-L1 may act as a cofactor for Smad3 to promote the process of lung fibrosis." (PMID 38263193, 2024). "Several investigators found that safflower injection may reduce bleomycin-induced pulmonary fibrosis in mice by inhibiting the TGF-β1/Smad3 signaling pathway and downregulating α-SMA expression." (PMID 38567353, 2024). "Mechanism study found that MSCs supernatant could inhibit TGF-β1-induced phosphorylation of Smad2 and Smad3 to suppress the activation of pulmonary fibrosis cells." (PMID 37580529, 2023). "And microRNA-29 could alleviate the occurrence of pulmonary fibrosis by downregulating the TGF-β/Smad3 signaling pathway in lung fibrosis mice." (PMID 36761779, 2023). "In addition, miR-29 is negatively regulated by TGF-β/Smad3 and has a potential therapeutic effect on bleomycin-induced pulmonary fibrosis." (PMID 37511199, 2023). "For instance, we did not investigate the detailed mechanism of the effect of avitinib on the TGF-β-mediated Smad3 signalling pathway, and the direct target of avitinib in the anti-pulmonary fibrosis process remains unclear." (PMID 36949426, 2023). "In addition, some small molecule compounds (nintedanib, pirfenidone, regorafenib, anlotinib, and imatinib) have been shown to alleviate bleomycin-induced pulmonary fibrosis by downregulating the TGF-β1/Smad3 signalling pathway." (PMID 36949426, 2023). "FOXO3 directly bound to SPON1 and its promoter, promoted the formation of SPON1 circRNA, inhibited the nuclear translocation of Smad3 through interaction with Smad3 and sponge Smad7 as the targeted miRNAs to promote Smad7 expression, and ultimately inhibited the progression of pulmonary fibrosis." (PMID 37416778, 2023). "Also, the TGF-β/Smad3 pathway plays an important role in pulmonary fibrosis, and inhibition of TGF-β/Smad3 activation can reduce the extent of pulmonary fibrosis." (PMID 36624433, 2023). "The beneficial effects of PRXT on pulmonary fibrosis may be attributed to its inhibition on GRK2 as well as Smad3 in lung fibroblasts." (PMID 37815883, 2023).